RN7SL700P (RNA, 7SL, cytoplasmic 700, pseudogene)
Gene: Miscellaneous RNA gene on chromosome 13 (47,458,941 to 47,459,234, reverse strand). Ensembl gene ENSG00000244521.
Homologues: Orthologues: chimpanzee Metazoa_SRP (99% identical), macaque Metazoa_SRP (93% identical). Paralogues in human: RN7SL1 (83% identical), RN7SL2 (83% identical), RN7SL3 (82% identical), RN7SL220P (80% identical), RN7SL304P (79% identical), RN7SL660P (79% identical), RN7SL448P (79% identical), RN7SL493P (79% identical), RN7SL566P (79% identical), RN7SL597P (79% identical), RN7SL769P (79% identical), RN7SL300P (78% identical), and 703 more.